EFEMP1 (EGF-like fibulin extracellular matrix protein 1)
Description:
Binds EGFR, the EGF receptor, inducing EGFR autophosphorylation and the activation of downstream signaling pathways. May play a role in cell adhesion and migration. May function as a negative regulator of chondrocyte differentiation. In the olfactory epithelium, it may regulate glial cell migration, differentiation and the ability of glial cells to support neuronal neurite outgrowth.
Synonyms: FIBL-3; FBLN3; FBNL; S1-5; MTLV; ARCL1D; DHRD; DRAD; GLC1H; MLVT
Tractability: Antibody: UniProt places it where antibodies can reach, with high confidence; its Gene Ontology location is reachable by antibodies, with high confidence; UniProt predicts a signal peptide or a membrane-spanning region. PROTAC: ubiquitination databases record sites on it.
Gene: Protein-coding gene on chromosome 2 (55,865,962 to 55,924,271, reverse strand). Ensembl gene ENSG00000115380.
Subcellular location: Secreted, extracellular space, extracellular matrix
Subcellular location (Human Protein Atlas): Mitochondria; Predicted to be secreted
Pathways (Reactome):
Extracellular matrix organization: Molecules associated with elastic fibres
Gene Ontology:
Molecular function: epidermal growth factor receptor activity; epidermal growth factor receptor binding; protein binding; extracellular matrix structural constituent; calcium ion binding
Biological process: camera-type eye development; embryonic eye morphogenesis; epidermal growth factor receptor signaling pathway; negative regulation of chondrocyte differentiation; peptidyl-tyrosine phosphorylation; post-embryonic eye morphogenesis; regulation of DNA-templated transcription; visual perception
Cellular component: extracellular exosome; extracellular matrix; extracellular region; mitochondrion; elastic fiber; non-collagenous component of interstitial matrix
Genetic constraint (gnomAD): Loss-of-function variants: 17 observed, 68.43 expected, observed/expected ratio (o/e) 0.25, 90% interval 0.17 to 0.37. The upper end of that interval is the gene's LOEUF score, 0.37, which puts it in group 1 of 6, group 1 being the genes least tolerant of losing a copy. Missense variants: 469 observed, 660.11 expected, observed/expected ratio (o/e) 0.71, 90% interval 0.66 to 0.77. Synonymous variants: 237 observed, 233.47 expected, observed/expected ratio (o/e) 1.02, 90% interval 0.91 to 1.13.
Gene-disease validity (ClinGen):
ClinGen rates the evidence that EFEMP1 causes each of these diseases.
Doyne honeycomb retinal dystrophy (autosomal dominant): Definitive.
open-angle glaucoma (autosomal dominant): Moderate. Chronic outflow obstruction of the eye's drainage canals that can lead to increased internal eye pressure and optic nerve damage.
Homologues: Orthologues: chimpanzee EFEMP1 (100% identical), dog EFEMP1 (96% identical), rabbit EFEMP1 (96% identical), pig EFEMP1 (95% identical), mouse Efemp1 (95% identical), rat Efemp1 (93% identical), macaque EFEMP1 (90% identical), guinea pig EFEMP1 (83% identical), tropical clawed frog efemp1 (65% identical), zebrafish si:ch73-173h19.3 (43% identical), zebrafish efemp1 (35% identical). Paralogues in human: EFEMP2 (48% identical), FBLN5 (40% identical), FBLN2 (31% identical), FBLN1 (30% identical), EYS (24% identical), VWDE (19% identical).
Diseases named in the same sentence as EFEMP1 in open-access papers:
EFEMP1 is named in the same sentence as 175 diseases in open-access papers, as found by Europe PMC text mining. Sharing a sentence is not in itself a finding about the gene and the disease. The quoted sentences say what the papers report.
glioma (31 papers, 2011 to 2026). A benign or malignant brain and spinal cord tumor that arises from glial cells (astrocytes, oligodendrocytes, ependymal cells). "GWAS studies have also found EFEMP1 variants to be associated with increased risk of two tumour types: glioma and breast cancer." (PMID 32911658, 2020). "In conclusion, we found a significant we found a significant association between rs603965 within CCND1 gene, rs1346787 and rs3791679 within EFEMP1 gene and increased glioma risk." (PMID 28380465, 2017). "In this study based on Chinese Han population, we found a significant association between rs603965 within CCND1 gene, rs1346787 and rs3791679 within EFEMP1 gene and increased glioma risk, after covariates adjustment." (PMID 28380465, 2017). "So in this study, we investigated the impact of interaction between CCND1 and EFEMP1 gene polymorphism on glioma risk." (PMID 28380465, 2017). "So in this study, we aimed to the impact of CCND1 and EFEMP1 gene polymorphism, and additional their gene-gene interactions and haplotype within EFEMP1 gene on glioma risk based on Chinese population." (PMID 28380465, 2017). "Logistic analysis showed the significant association of rs603965 within CCND1 gene, rs1346787 and rs3791679 in EFEMP1 gene with increased glioma risk, after adjustment for gender, age, smoking and alcohol drinking." (PMID 28380465, 2017). "Polymorphism in rs603965 within CCND1 gene and rs1346787 within EFEMP1 gene and its gene- gene interaction were associated with increased glioma risk." (PMID 28380465, 2017). "We report in this study the identification of such an ETSP from fourteen expression constructs of EFEMP1 having a deletion and/or mutation, based on effects generated from their over-expression, in vitro and in vivo, in two syngeneic glioma cell lines." (PMID 27713911, 2016). "To date, both tumor suppressive functions and oncogenic activities have been associated with EFEMP1, such as glioma." (PMID 25987128, 2015). "The mechanisms underlying EFEMP1's tumor suppressive function in glioma has been shown to be mediated through EFEMP1's binding to EGFR." (PMID 25594013, 2014). "EFEMP1, was another gene which has been reported association with glioma risk recently." (PMID 28380465, 2017). "We found a significant two-locus model (p=0.0010) involving rs603965 within CCND1 gene and rs1346787 within EFEMP1 gene, participants with rs603965 - GA or AA and rs1346787- AG or GG genotype have the highest glioma risk, compared to participants with rs603965 - GG and rs1346787- AA genotype." (PMID 28380465, 2017). "We also found a significant two-locus model (p=0.0010) involving rs603965 within CCND1 gene and rs1346787 within EFEMP1 gene, participants with rs603965 - GA or AA and rs1346787- AG or GG genotype have the highest glioma risk, compared to participants with rs603965 - GG and rs1346787- AA genotype." (PMID 28380465, 2017). "The results of this study suggest that CCND1 G870A genetic variants may modify the influence of EFEMP1- rs1346787 gene on glioma risk." (PMID 28380465, 2017). "Thus suppression of VEGFA is likely only one of several probable mechanisms underlying EFEMP1 suppression of glioma growth and EFEMP1 exhibits some VEGF-independent anti-tumor effects." (PMID 21955618, 2011). "Study showed that EFEMP1 is a paracrine activator of Notch signaling in endothelial cells and promotes glioma angiogenesis." (PMID 38715099, 2024). "They confirmed anti-tumor efficacy against EFEMP1-secreting solid tumors (gliomas, lung cancers and kidney cancer)." (PMID 34204134, 2021). "In glioma, miR-338-5p targeting EFEMP1 increases tumor apoptosis and suppresses tumor proliferation, migration and invasion." (PMID 34204134, 2021). "Previous report has indicated that EFEMP1 is an oncogene in glioma, while other findings elucidate the opposite effect of EFEMP1 in glioma." (PMID 32056133, 2020).
glioma (continued). "Another study showed that suppression of EFEMP1 reduced migration, invasion and promote apoptosis in brain cells (glioma)." (PMID 30008265, 2018). "EFEMP1 was found to be highly upregulated in gliomas and enhanced substrate-specific glioma cell adhesion and motility." (PMID 25987128, 2015). "In contrast, only about ten studies have examined the pro-tumor effects of EFEMP1, comprising only five tumor types (pancreatic carcinoma, glioma, cervical cancer, ovarian carcinoma and pleural mesothelioma)." (PMID 25987128, 2015). "We demonstrated EGFR's unfavorable prognostic values in a subtype of gliomas expressing a low level of EFEMP1, which was consistent with EFEMP1's anti-EGFR function." (PMID 26307682, 2015). "An unfavorable prognostic value of EFEMP1 was also observed in a subtype of gliomas expressing a low level of EGFR." (PMID 26307682, 2015). "Our prognosis study of glioma patients classified according to EFEMP1 expression level, demonstrated, for the first time, a significant unfavorable value for EGFR." (PMID 25594013, 2014). "In the EFEMP1-low glioma subset (N = 101), EGFR showed a significant, unfavorable, patient prognosis, with HR = 2.1 and a 95% confidence interval = (1.3 – 3.4)." (PMID 25594013, 2014). "EFEMP1, a fibulin-like extracellular protein, exerts both tumor suppressive and oncogenic effects in various cancers and glioma cell models." (PMID 25594013, 2014). "In 166 glioma cDNA samples from that study, (95 GBMs, 36 AAs, and 35 OTs), we quantified EFEMP1 and obtained the absolute ratio of EFEMP1 to ACTB, using same-standard-based, real-time qRT-PCR." (PMID 25594013, 2014). "A glioma prognostic model also suggests EFEMP1's context-dependent oncogenic function in gliomas expressing low levels of EGFR." (PMID 25594013, 2014). "EGF-containing fibulin-like extracellular matrix protein 1 (EFEMP1) is a secreted protein that was determined to inhibit cancerous glioma growth through the reduction of EGFR levels and intracellular AKT phosphorylation." (PMID 26056585, 2014). "Here we showed a similar tumor suppressive effect from Dox-induced overexpression of EFEMP1 in glioma cell line U87 and primary culture G43-SA, based on a comparison with the empty-vector control." (PMID 25594013, 2014). "It has been shown in glioma stem-like cells EFEMP1 activates/depends NOTCH signaling to promote cell invasiveness." (PMID 25594013, 2014). "We have previously reported on the tumor suppressive effect of EFEMP1 in GBM and EFEMP1's function in reducing the EGFR signaling activities in glioma cells." (PMID 24282558, 2013). "In the research of pancreatic adenocarcinoma, cervical cancer and glioma, increased expression of EFEMP1 has been reported; EFEMP1 plays a role in metastasis and development, and thus links it to poor prognosis." (PMID 24236050, 2013). "EFEMP1-mediated suppression of glioma-cell expression of VEGFA would result in the suppression of VEGFA stimulation of angiogenesis, which is in addition to EFEMP1's direct inhibition of endothelial cells sprouting." (PMID 21955618, 2011). "The overall results of this study revealed a role for EFEMP1 in the suppression of glioma growth, via independent blockade of EGFR and AKT signaling pathways and the repression of VEGFA-induced angiogenesis." (PMID 21955618, 2011). "In glioma cells that were treated by exogenous EFEMP1 protein or over-expressed endogenous EFEMP1, the EGFR level was reduced and AKT signaling activity attenuated." (PMID 21955618, 2011). "The strikingly different effect of EFEMP1 on glioma-cell growth potential in vitro and in vivo suggested involvement of tissue or environmental factors, and we strongly suspected angiogenesis to play a key role." (PMID 21955618, 2011). "Human high-grade glioma cell lines and primary cultures were engineered to express ectopic EFEMP1, a small hairpin RNA of EFEMP1, or treated with exogenous recombinant EFEMP1 protein." (PMID 21955618, 2011).
glioma (continued). "We then further investigated the effect of reducing EFEMP1 levels (via lentiviral expression of shRNA of EFEMP1 - shEFEMP1) on glioma cell tumorigenicity." (PMID 21955618, 2011). "This suggested that inhibition of angiogenesis was only partly responsible for EFEMP1's impact on glioma development." (PMID 21955618, 2011). "In glioma cells, EFEMP1 was shown to enhance in vitro substrate-specific cell adhesion and promote cell motility and dispersion." (PMID 21955618, 2011). "We thus carried out an in-depth study of EFEMP1 expression as a prognostic marker in the most malignant grade of glioma, glioblastoma multiforme (GBM)." (PMID 21955618, 2011). "This is the first demonstration of EFEMP1's role in the regulation of glioma cell invasion in an i.c. xenograft system." (PMID 21955618, 2011). "They showed that the lockdown of the fibulin-3 gene EFEMP1 increased apoptosis and impaired intracranial tumor growth, which was correlated with low expression levels of the genes related to Notch signaling in glioma samples." (PMID 35473807, 2022). "EFEMP1 was shown to suppress the glioma growth by modulating the tumour microenvironment." (PMID 34936728, 2021). "It is worth highlighting that some of the strongest evidence implicating fibulin-3 causally in tumour progression has arisen in the context of glioma, conceptually consistent with the implication of EFEMP1 in a genetic susceptibility to glioma via GWAS." (PMID 32911658, 2020). "Notably, some of these conditions have also been found to involve increased fibulin-3 expression levels (CTS and glioma), so it is possible that this specific SNP in the enhancer region leads to pathological EFEMP1 overexpression." (PMID 32911658, 2020). "The results about the function of EFEMP1 in glioma were conflicting." (PMID 28380465, 2017). "Moreover, EFEMP1 expression correlates with the expression levels of Notch-dependent genes and is a marker of Notch activation in patient-derived glioma samples." (PMID 25987128, 2015). "Interestingly, the contradictory role of EFEMP1 in glioma prognosis was shown in the degrees of i.c. tumorigenicity of U251-NS associated with different inoculum size (100k, 10k, and 1k cells)." (PMID 26307682, 2015). "EFEMP1 suppressed EGF internalization in both of the glioma cell lines (U251 and G43-SA) examined." (PMID 25594013, 2014). "In addition, EFEMP1 levels were higher in gliomas of the mesenchymal subtype compared to the proneural subtype which have poor overall survival compared to the other subtypes." (PMID 24495907, 2014). "Although EFEMP1's anti-cancer activity has most commonly been attributed to its anti-angiogenic effects, we showed for gliomas that EFEMP1's binding to EGFR accounts for its suppression of the intracranial tumorigenicity of glioma cells expressing high levels of EGFR." (PMID 25594013, 2014). "The tumor-suppressive effect of EFEMP1 to glioma cells may also be applicable to other cancer types that have hyperactivation of EGFR and AKT signaling pathways." (PMID 21955618, 2011). "In addition to the overall improvement of mouse survival resulting from EFEMP1 over-expression, MRI data of i.c. glioma morphologies revealed EFEMP1's function in potentiating glioma-cell infiltration, as shown by in vitro studies." (PMID 21955618, 2011). "While more studies are needed to further define the role of EFEMP1 (i.e. anti-angiogenic vs. pro-invasive), results from this study provide a mechanistic rationale on developing EFEMP1, or EFEMP1-derived signaling peptide, as a new potent therapy for patients with high-grade gliomas." (PMID 21955618, 2011). "A potential oncogenic role of EFEMP1 was identified in cervical carcinoma and pleural mesothelioma, and has been found in a human pancreatic carcinoma-derived cell line, a chemically induced rat glioma cell line, and in human glioma-derived stem-like glioma cells." (PMID 25594013, 2014).
glioma (continued). "Glioma risks were higher in carriers of homozygous mutant of rs603965 within CCND1 gene, rs1346787 and rs3791679 in EFEMP1 gene than those with wild-type homozygotes, OR (95%CI) were 1.67 (1.23-2.02), 1.59 (1.25-2.01) and 1.42 (1.15-1.82), respectively." (PMID 28380465, 2017). "In certain glioma cells with activation of NTOCH signaling, EFEMP1 has been shown to enhance in vitro substrate-specific cell adhesion and promote cell motility and dispersion." (PMID 27713911, 2016). "To determine if there is a correlation between protein expression levels of EFEMP1 and EGFR in gliomas, we tested a tissue microarray (TMA) of astrocytic gliomas (N = 65) with antibodies for EGFR and EFEMP1." (PMID 25594013, 2014). "In gliomas where EFEMP1 expression, and thus the anti-EGFR effect of EFEMP1, was suppressed, heightened levels of EGFR expression were associated with unfavorable patient outcomes in prognostic models." (PMID 25594013, 2014). "Cox proportional hazards regression analysis was then carried out using both log-scaled ratios of EFEMP1 and EGFR vs ACTB (continuous variables) and dichotomized variables for these 166 gliomas." (PMID 25594013, 2014). "In a prior study, we showed that human recombinant (hr) EFEMP1 protein reduced the EGFR level and AKT phosphorylation (pAKT) in 48-hr treated glioma cell lines." (PMID 25594013, 2014). "In the two PTEN null/mutant human glioma cell lines (U251HF and SNB19) under serum-free conditions, the suppressive effect of EFEMP1 on AKT phosphorylation was seen 24 hours after the treatment, while total EGFR reduction occurred a day later." (PMID 21955618, 2011). "Recent years, the genetic factors including single nucleotide polymorphisms (SNPs) may also exert effects on the development of glioma, including Cyclin D1 (CCND1) and EFEMP1 gene." (PMID 28380465, 2017). "In malignant gliomas, EFEMP1 secreted by glioma cells could activate DLL4-Notch signaling to induce pro-angiogenic behavior and promote glioma cell motility and invasion." (PMID 27351229, 2016). "In addition, EFEMP1 has been shown to be overexpressed concomitantly with MMP-2, MMP-9 and ADAMTS-5 in glioma." (PMID 25987128, 2015). "Anti-EGFR function of EFEMP1 had on the expression of EGFR and glioma patient prognosis." (PMID 25987128, 2015). "EFEMP1 is not significantly expressed in normal brain, however, it is highly expressed in high-grade gliomas, where it promotes tumor growth and invasion." (PMID 24495907, 2014). "It suggests an oncogenic role of EFEMP1 in gliomas that do not have high EGFR expression, or where tumor growth was not largely driven by EGFR-activated signaling." (PMID 25594013, 2014). "We have shown that EFEMP1-mediated down-regulation of AKT signaling occurs in PTEN null/mutant glioma cells under serum-starvation conditions but not in serum-containing medium." (PMID 21955618, 2011). "In contrast, in the EFEMP1-high glioma subset (N = 65), EGFR data analysis had no prognostic value." (PMID 25594013, 2014). "However, to date, there has been no in vivo study of EFEMP1 effects on human glioma biology." (PMID 21955618, 2011). "In the EGFR-low glioma subset (N = 115), EFEMP1 data analysis showed a significant, unfavorable, patient prognosis, with HR = 1.7 and a 95% confidence interval = (1.1 – 2.7), while in the EGFR-high glioma subset (N = 51), the EFEMP1 data lacked any significant prognostic value." (PMID 25594013, 2014).